UTP15 (UTP15 small subunit processome component)
Description:
Ribosome biogenesis factor. Involved in nucleolar processing of pre-18S ribosomal RNA. Required for optimal pre-ribosomal RNA transcription by RNA polymerase I. Part of the small subunit (SSU) processome, first precursor of the small eukaryotic ribosomal subunit. During the assembly of the SSU processome in the nucleolus, many ribosome biogenesis factors, an RNA chaperone and ribosomal proteins associate with the nascent pre-rRNA and work in concert to generate RNA folding, modifications, rearrangements and cleavage as well as targeted degradation of pre-ribosomal RNA by the RNA exosome.
Synonyms: FLJ12787; NET21; FLJ23637
Tractability: Small molecule: a structure with a bound ligand is known. PROTAC: UniProt records ubiquitination sites on it; ubiquitination databases record sites on it; its protein half-life has been measured.
Gene: Protein-coding gene on chromosome 5 (73,565,443 to 73,583,380, forward strand). Ensembl gene ENSG00000164338.
Subcellular location: Nucleus, nucleolus
Subcellular location (Human Protein Atlas): Endoplasmic reticulum; Nucleoli
Pathways (Reactome):
Metabolism of RNA: Major pathway of rRNA processing in the nucleolus and cytosol; rRNA modification in the nucleus and cytosol
Gene Ontology:
Molecular function: protein binding; RNA binding
Biological process: positive regulation of rRNA processing; positive regulation of transcription by RNA polymerase I; ribosomal small subunit biogenesis; maturation of SSU-rRNA; rRNA processing
Cellular component: cytoplasm; fibrillar center; nucleolus; small-subunit processome; nucleoplasm; t-UTP complex
Genetic constraint (gnomAD): Loss-of-function variants: 5 observed, 54.27 expected, observed/expected ratio (o/e) 0.0921, 90% interval 0.047 to 0.19. The upper end of that interval is the gene's LOEUF score, 0.19, which puts it in group 1 of 6, group 1 being the genes least tolerant of losing a copy. Missense variants: 456 observed, 597.58 expected, observed/expected ratio (o/e) 0.76, 90% interval 0.71 to 0.82. Synonymous variants: 199 observed, 208.66 expected, observed/expected ratio (o/e) 0.95, 90% interval 0.85 to 1.07.
Homologues: Orthologues: chimpanzee UTP15 (99% identical), macaque UTP15 (99% identical), pig UTP15 (96% identical), rabbit UTP15 (95% identical), dog UTP15 (95% identical), guinea pig UTP15 (95% identical), rat Utp15 (91% identical), mouse Utp15 (90% identical), tropical clawed frog utp15 (67% identical), zebrafish utp15 (56% identical), Drosophila melanogaster CG3071 (37% identical), Caenorhabditis elegans Y23H5B.5 (29% identical).